LYAR (Ly1 antibody reactive)
Description:
Plays a role in the maintenance of the appropriate processing of 47S/45S pre-rRNA to 32S/30S pre-rRNAs and their subsequent processing to produce 18S and 28S rRNAs. Also acts at the level of transcription regulation. Along with PRMT5, binds the gamma-globin (HBG1/HBG2) promoter and represses its expression. In neuroblastoma cells, may also repress the expression of oxidative stress genes, including CHAC1, HMOX1, SLC7A11, ULBP1 and SNORD41 that encodes a small nucleolar RNA. Preferentially binds to a DNA motif containing 5'-GGTTAT-3'. Negatively regulates the antiviral innate immune response by targeting IRF3 and impairing its DNA-binding activity. In addition, inhibits NF-kappa-B-mediated expression of pro-inflammatory cytokines. Stimulates phagocytosis of photoreceptor outer segments by retinal pigment epithelial cells (By similarity). Prevents nucleolin/NCL self-cleavage, maintaining a normal steady-state level of NCL protein in undifferentiated embryonic stem cells (ESCs), which in turn is essential for ESC self-renewal (By similarity).
Synonyms: ZLYAR; ZC2HC2
Tractability: PROTAC: UniProt records ubiquitination sites on it; ubiquitination databases record sites on it; its protein half-life has been measured.
Gene: Protein-coding gene on chromosome 4 (4,267,572 to 4,290,196, reverse strand). Ensembl gene ENSG00000145220.
Subcellular location: Nucleus; Nucleus, nucleolus; Cytoplasm; Cell projection, cilium, photoreceptor outer segment
Subcellular location (Human Protein Atlas): Nucleoli rim; Nucleoli; Nucleoplasm
Gene Ontology:
Molecular function: DNA binding; DNA-binding transcription factor binding; identical protein binding; protein binding; RNA binding; transcription regulator inhibitor activity
Biological process: erythrocyte development; negative regulation of innate immune response; negative regulation of transcription by RNA polymerase II; positive regulation of transcription by RNA polymerase I; rRNA processing; positive regulation of phagocytosis
Cellular component: cytoplasm; nucleolus; nucleoplasm; nucleus; photoreceptor outer segment
Genetic constraint (gnomAD): Loss-of-function variants: 19 observed, 27.83 expected, observed/expected ratio (o/e) 0.68, 90% interval 0.47 to 1. The upper end of that interval is the gene's LOEUF score, 1, which puts it in group 4 of 6, group 1 being the genes least tolerant of losing a copy. Missense variants: 354 observed, 348.61 expected, observed/expected ratio (o/e) 1.02, 90% interval 0.93 to 1.11. Synonymous variants: 134 observed, 125.66 expected, observed/expected ratio (o/e) 1.07, 90% interval 0.93 to 1.23.
Homologues: Orthologues: macaque LYAR (97% identical), chimpanzee LYAR (97% identical), pig LYAR (78% identical), dog LYAR (77% identical), rat Lyar (77% identical), mouse Lyar (75% identical), rabbit LYAR (72% identical), tropical clawed frog lyar (51% identical), guinea pig Lyar (40% identical), zebrafish lyar (26% identical), Drosophila melanogaster CG12909 (26% identical), Caenorhabditis elegans C16C10.8 (25% identical).